PRKCQ-AS1 (PRKCQ antisense RNA 1)
Synonyms: ENST00000414894.1
Gene: Long non-coding RNA gene on chromosome 10 (6,580,419 to 6,616,921, forward strand). Ensembl gene ENSG00000237943.
Diseases named in the same sentence as PRKCQ-AS1 in open-access papers:
PRKCQ-AS1 is named in the same sentence as 12 diseases in open-access papers, as found by Europe PMC text mining. Sharing a sentence is not in itself a finding about the gene and the disease. The quoted sentences say what the papers report.
neuroblastoma (1 paper, 2025). Neuroblastoma (NB) is the most common solid, extracranial childhood tumor. "Taken together, the data suggest that PRKCQ‐AS1 is overexpressed in MYCNnonamplified neuroblastoma cells due to association with the SE_513 super‐enhancer." (PMID 40103284, 2025). "The data suggests that PRKCQ‐AS1 is overexpressed in MYCN nonamplified neuroblastoma cells due to transcriptional super‐enhancers." (PMID 40103284, 2025). "In summary, this study identifies PRKCQ‐AS1 as the lncRNA most overexpressed in MYCN nonamplified, compared with MYCN‐amplified, neuroblastoma cell lines, and transcriptional super‐enhancers as the factor responsible for PRKCQ‐AS1 overexpression." (PMID 40103284, 2025). "Importantly, while PRKCQ‐AS1 or MSI2 overexpression augments MYCN nonamplified neuroblastoma cell proliferation, MSI2 knockdown reverses PRKCQ‐AS1‐induced neuroblastoma cell proliferation, and PRKCQ‐AS1 knockdown blocks MSI2‐mediated neuroblastoma cell proliferation." (PMID 40103284, 2025). "Our RNA sequencing has identified PRKCQ‐AS1 as the lncRNA most overexpressed in MYCN nonamplified, compared with MYCN‐amplified, human neuroblastoma cell lines." (PMID 40103284, 2025).
cancer (1 paper, 2024). A tumor composed of atypical neoplastic, often pleomorphic cells that invade other tissues. "Moreover, urothelial cancer associated 1 (UCA1) and PRKCQ antisense RNA 1 (PRKCQ-AS1), were associated with proliferation, migration and apoptosis, especially in cancers." (PMID 38291538, 2024).
PRKCQ-AS1 also shares sentences with these, for which no sentence is quoted: allergic rhinitis (1 paper); asthma (1); autoimmune disease (1); eczema (1); leukemia (1); mood disorder (1); multiple myeloma (1); rheumatoid arthritis (1); tumor (1); unipolar depression (1).